RNF2 (ring finger protein 2)
Description:
E3 ubiquitin-protein ligase that mediates monoubiquitination of 'Lys-119' of histone H2A (H2AK119Ub), thereby playing a central role in histone code and gene regulation. H2AK119Ub gives a specific tag for epigenetic transcriptional repression and participates in X chromosome inactivation of female mammals. May be involved in the initiation of both imprinted and random X inactivation (By similarity). Essential component of a Polycomb group (PcG) multiprotein PRC1-like complex, a complex class required to maintain the transcriptionally repressive state of many genes, including Hox genes, throughout development. PcG PRC1 complex acts via chromatin remodeling and modification of histones, rendering chromatin heritably changed in its expressibility. E3 ubiquitin-protein ligase activity is enhanced by BMI1/PCGF4. Acts as the main E3 ubiquitin ligase on histone H2A of the PRC1 complex, while RING1 may rather act as a modulator of RNF2/RING2 activity (Probable). Association with the chromosomal DNA is cell-cycle dependent. In resting B- and T-lymphocytes, interaction with AURKB leads to block its activity, thereby maintaining transcription in resting lymphocytes (By similarity). Also acts as a negative regulator of autophagy by mediating ubiquitination of AMBRA1, leading to its subsequent degradation (By similarity).
Synonyms: RING1b; BAP1; DING; HIPI3; BAP-1; RING2; LUSYAM
Tractability: Small molecule: a structure with a bound ligand is known. PROTAC: UniProt records ubiquitination sites on it; ubiquitination databases record sites on it; its protein half-life has been measured.
Gene: Protein-coding gene on chromosome 1 (185,044,865 to 185,102,603, forward strand). Ensembl gene ENSG00000121481.
Subcellular location: Nucleus; Cytoplasm; Chromosome
Subcellular location (Human Protein Atlas): Nucleoplasm; Nuclear bodies
Pathways (Reactome):
Metabolism of proteins: SUMOylation of DNA damage response and repair proteins; SUMOylation of DNA methylation proteins; SUMOylation of RNA binding proteins; SUMOylation of chromatin organization proteins; SUMOylation of transcription cofactors
Gene expression (Transcription): RUNX1 interacts with co-factors whose precise effect on RUNX1 targets is not known; Transcriptional Regulation by E2F6
Cellular responses to stimuli: Oxidative Stress Induced Senescence
Developmental Biology: Differentiation of naive CD4+ T cells to T helper 2 cells (Th2 cells)
Signal Transduction: Regulation of PTEN gene transcription
Gene Ontology:
Molecular function: chromatin binding; protein binding; RING-like zinc finger domain binding; ubiquitin protein ligase activity; ubiquitin-protein transferase activity; zinc ion binding; histone H2AK119 ubiquitin ligase activity
Biological process: chromatin remodeling; epigenetic regulation of gene expression; negative regulation of transcription by RNA polymerase II; heterochromatin formation; negative regulation of DNA-templated transcription; positive regulation of DNA-templated transcription; germ cell development; protein ubiquitination
Cellular component: MLL1 complex; nuclear body; nucleoplasm; nucleus; PcG protein complex; PRC1 complex; ubiquitin ligase complex; chromatin; chromosome; cytoplasm; euchromatin; heterochromatin; ribonucleoprotein complex; sex chromatin
Genetic constraint (gnomAD): Loss-of-function variants: 5 observed, 32.74 expected, observed/expected ratio (o/e) 0.15, 90% interval 0.079 to 0.32. The upper end of that interval is the gene's LOEUF score, 0.32, which puts it in group 1 of 6, group 1 being the genes least tolerant of losing a copy. Missense variants: 246 observed, 410.72 expected, observed/expected ratio (o/e) 0.6, 90% interval 0.54 to 0.67. Synonymous variants: 129 observed, 135.64 expected, observed/expected ratio (o/e) 0.95, 90% interval 0.82 to 1.1.
Homologues: Orthologues: chimpanzee RNF2 (100% identical), macaque RNF2 (100% identical), mouse Rnf2 (99% identical), pig RNF2 (99% identical), dog RNF2 (99% identical), rat Rnf2 (99% identical), tropical clawed frog rnf2 (94% identical), zebrafish rnf2 (89% identical), guinea pig RNF2 (82% identical), Drosophila melanogaster Psc (36% identical), Drosophila melanogaster Su(z)2 (12% identical). Paralogues in human: RING1 (65% identical), PCGF3 (18% identical), BMI1 (18% identical), PCGF5 (16% identical), PCGF2 (16% identical), PCGF6 (15% identical), PCGF1 (15% identical).
Diseases named in the same sentence as RNF2 in open-access papers:
RNF2 is named in the same sentence as 87 diseases in open-access papers, as found by Europe PMC text mining. Sharing a sentence is not in itself a finding about the gene and the disease. The quoted sentences say what the papers report.
breast carcinoma (14 papers, 2014 to 2025). "In the current study, we found that the RING finger E3 ubiquitin ligase RNF2 associates with the ERα protein in the nucleus in breast cancer cells, which subsequently facilitates breast cancer cell progression by stabilizing the ERα protein." (PMID 36271315, 2023). "In contrast to its canonical function, RING1B (encoded by RNF2) is predominantly recruited to enhancers and specifically regulates oncogenic transcriptional programs in different breast cancer subtypes." (PMID 30139998, 2018). "To further investigate the regulation of breast cancer cell phenotype by RNF2, we overexpressed RNF2 in MCF-7." (PMID 36271315, 2023). "In conclusion, our findings suggest that RNF2 is a novel modulatory component of ERα signaling in human breast cancer." (PMID 36271315, 2023). "To investigate the expression of RNF2 at the level of breast cancer proteins, we analyzed RNF2 expression in breast cancer patient samples by immunohistochemistry (IHC)." (PMID 36271315, 2023). "The cell phenotype impact of RNF2 was further validated in another ERα-positive breast cancer cell line." (PMID 36271315, 2023). "In our study, we found that RNF2 is required for breast cancer progression and estrogen signaling activity and that RNF2 can modulate ERα signaling by controlling ERα protein ubiquitination and stability." (PMID 36271315, 2023). "The findings of our current study result in conclusions similar to those of these two previous studies, namely, that RNF2 is elevated in ER+ breast cancer and promotes ER signaling target gene transcription." (PMID 36271315, 2023). "In our study, RNF2 facilitated ERα signaling and promoted cell proliferation in breast cancer by enhancing ERα stability, possibly by inhibiting ERα K48-linked polyubiquitination." (PMID 36271315, 2023). "Further analysis of GEO data (GSE137579) from breast cancer cells showed that RNF2 depletion significantly inhibited estrogen response gene expression." (PMID 36271315, 2023). "All these data show that RNF2 expression is positively correlated with estrogen signaling in clinical breast cancer samples." (PMID 36271315, 2023). "Our initial analysis of the TCGA breast cancer data set indicated that patients with ER+ breast cancer and high levels of RNF2 survive longer than patients with lower RNF2 levels." (PMID 30139998, 2018). "Here, we show that RNF2, encoding RING1B, and canonical PRC1 (cPRC1) genes are overexpressed in breast cancer." (PMID 30139998, 2018). "Here we show that high levels of RNF2 in patients with ER+ breast cancer tumors correlate with good survival outcome, while high RNF2 levels in patients with basal breast cancer correlate with lower survival probability." (PMID 30139998, 2018). "In contrast, patients with basal breast cancer and high levels of RNF2 have a lower survival probability." (PMID 30139998, 2018). "We found that RNF2 was amplified in up to 22% of breast cancers and cPRC1 genes were amplified in a large number of samples." (PMID 30139998, 2018). "We further investigated the effect of RNF2 on estrogen signaling in breast cancer cells." (PMID 36271315, 2023). "In conclusion, our study implicates nongenomic regulation by RNF2 on ERα protein stability and suggests that targeting RNF2 could be a promising strategy for breast cancer treatments." (PMID 36271315, 2023). "Interestingly, RNF2 has been reported to correlate with the occurrence and progression of several human malignancies, including breast cancer." (PMID 36271315, 2023). "RNF2 depletion inhibited breast cancer cell progression and ERα signaling activity." (PMID 36271315, 2023). "Among them, increasing evidence has shown that RNF2 contributes to influence clinical characteristics of many types of cancers, including hepatocellular carcinoma, melanoma, prostate cancer, breast cancer, pancreatic cancer, gastric cancer and bladder urothelial carcinoma." (PMID 38033505, 2023).
breast carcinoma (continued). "Interestingly, RNF2 expression is elevated in breast cancer samples and correlates with ERα target gene expression." (PMID 36271315, 2023). "On this basis, targeting RNF2 to subsequently block its stabilizing effects on the ERα protein could be a plausible strategy for inhibiting breast cancer growth." (PMID 36271315, 2023). "Specifically, it is necessary to examine the regulatory role of RNF2 in TCF7L1-mediated breast cancer metastasis, as well as to explore whether RNF2-mediated regulation of TCF7L1 occurs only at the cellular level or requires other components." (PMID 37957244, 2023). "Furthermore, RNF2 can stabilize ERα protein, regulating the progression of breast cancer; this mechanism may also function similarly in cervical cancer." (PMID 40809844, 2025). "Furthermore, several studies have shown that RNF2 is closely related to the ER in breast cancer." (PMID 36271315, 2023). "RNF2, a key E3 ubiquitin ligase within the RING finger protein family, exhibits upregulated expression in various cancers including breast cancer, colorectal cancer, and gastric cancer, and is closely associated with tumor initiation and progression." (PMID 40809844, 2025). "In the poorly differentiated breast cancer cell line, 4T1, which prominently expresses TCF7L1, a cycloheximide assay was performed, which confirmed that the overexpression of RNF2 decreased the stability of TCF7L1." (PMID 37957244, 2023). "RNF2 is the core subunit of PRC1, which is a negative regulator of anti-tumor immunity in various human cancers, including breast cancer." (PMID 36553670, 2022). "In agreement with survival prognoses of patients with different breast cancer subtypes and RNF2 expression levels, RING1B differentially regulates the metastatic potential of TNBC and ER+ breast cancer cells." (PMID 30139998, 2018). "Compared to RING1 which is not amplified, RNF2 amplification correlated to its significant overexpression in breast cancer compared to normal breast tissues, regardless of breast cancer subtype." (PMID 30139998, 2018). "However, RNF2, PCGF2, and CBX2/4/8 expression was higher in all four breast cancer stages compared to normal breast tissue, suggesting that their overexpression was not predictive of breast cancer aggressiveness." (PMID 30139998, 2018).
gastric cancer (10 papers, 2015 to 2025). A primary or metastatic malignant neoplasm involving the stomach. "Finally, the expression of RASSF10 and NPM positively correlated with the survival of patients with gastric cancer, and the reverse was observed with RNF2 expression, which suggests their association with gastric cancer progression." (PMID 34224728, 2021). "Collectively, these observations suggest the clinical significance of RASSF10, NPM, and RNF2 expression on gastric cancer prognosis." (PMID 34224728, 2021). "Correlation analysis clearly indicates that higher expression of RASSF10 and NPM correlates with better patient survival; in contrast, higher expression of RNF2 correlated with poor survival of patients with gastric cancer." (PMID 34224728, 2021). "In conclusion, RASSF10 is an important downstream target of RNF2 and the RASSF10/NPM/GADD45a/RNF2 feedback cascade may be used as a new biomarker for diagnosis and novel drug target for the therapy of gastric cancer." (PMID 34224728, 2021). "LINC00665 can promote tumorigenesis of gastric cancer via regulating miR-149-3p and RNF2." (PMID 33407473, 2021). "Interestingly, the expression of RNF2 as well as knockdown of NPM in gastric cancer cells enhance RASSF10 ubiquitination and destabilization, and the reverse was noticed with depletion of endogenous RNF2 by shRNA or ectopic expression of NPM." (PMID 34224728, 2021). "Collectively, our data suggest that RASS10/NPM/RNF2 feedback signaling cascade may act as a potential drug target to identify novel therapeutics for gastric cancers." (PMID 34224728, 2021). "Finally, our findings provide insights into the mode of action of the RASSF10/NPM/RNF2 signaling cascade on controlling cell proliferation and may represent a novel therapeutic avenue for the prevention of gastric cancer metastasis." (PMID 34224728, 2021). "Interestingly, the Kaplan–Meier plot analysis shows a positive correlation of RASSF10 and NPM expression with greater gastric cancer patient survival and the reverse with expression of RNF2, suggesting that they may have a role in cancer progression." (PMID 34224728, 2021). "Overexpression of RNF2 is positively correlated with progression of many cancers, including HCC, melanoma, pancreatic cancer, and gastric cancer." (PMID 36199791, 2022). "In gastric cancer, RNF2 and GRP78 are upregulated through the LINC00665/miR-149-3p axis and LINC00665/miR-379-5p axis, respectively, to promote gastric cancer progression." (PMID 35563845, 2022). "In gastric cancer, long non-coding RNA LINC00665 was involved in tumorigenesis via the miR-149-3p/RNF2 axis." (PMID 35251139, 2022). "In support of this, the survival plot analysis using data from TCGA database showed a negative correlation of RNF2 expression with poor patient survival, which suggests its role in gastric cancer progression." (PMID 34224728, 2021). "Furthermore, an inverse correlation was observed between RNF2 and RASSF10 expression in Indian gastric cancer cohorts." (PMID 34224728, 2021). "The qRT-PCR experiments were designed to detect the expression levels of the top 5 ranking HAX1, RNF2, PIM3, TPP1 and CAV1 genes in addition to the seed proteins ABCB1, AKT1 and BCL2 in both the SGC7901 gastric cancer cell line and the Adriamycin resistant SGC7901/ADR cell line." (PMID 26039373, 2015).
pancreatic cancer (10 papers, 2014 to 2023). "Interestingly several studies published up to now described worsening of prognoses with increased RNF2 expression in cancers of pancreas, esophagus, liver, urinary bladder and ovary." (PMID 29707138, 2018). "Although the function of RNF2 has not been determined in prostate cancer progression, knockdown of RNF2 by siRNA abolished SNAIL-mediated E-cadherin repression and induced cell migration in pancreatic cancer cells." (PMID 27340776, 2016).
melanoma (9 papers, 2016 to 2023). A malignant, usually aggressive tumor composed of atypical, neoplastic melanocytes. "However, analysis of the intratumoral expression of RNF2 in a relation to the patients’ survival demonstrated that high expression levels exceeding 70% of cells of primary melanomas and 75% of cells of the nodal metastases were associated with a longer survival." (PMID 29707138, 2018). "The same study demonstrated also that RNF2 supports anchorage independent proliferation of melanoma cells through up-regulation of cyclin D2 due to activation of CCND2 gene." (PMID 29707138, 2018). "Molecular analyses involving melanoma cell lines with enforced RNF2 expression demonstrated a presence of the RNF2 occupancy sites in vicinity of transcription start sites of 3465 genes." (PMID 29707138, 2018). "The expression of RNF2 in a normal skin surrounding benign nevi and primary melanomas was detected in ca. 20% of keratinocytes and ca. 40% of melanocytes, usually displaying weak (+) staining intensity." (PMID 29707138, 2018). "Recent studies involving melanoma cell lines suggest that enhanced expression of epigenetic regulator RNF2 supports proliferation and promotes metastasis." (PMID 29707138, 2018). "Higher expression levels of the protein are reflected in significant increase in the percentage of the RNF2 – positive cells, also those with a strong staining, already in the early stage melanomas compared to nevi and normal skin." (PMID 29707138, 2018). "The main aim of this work was the assessment of a suitability of intratumoral RNF2 expression in human melanoma as potential prognostic marker." (PMID 29707138, 2018). "RNF2 was detected immunohistochemically in standard formalin-fixed paraffin-embedded samples of 9 benign nevi, 60 melanomas and 24 nodal metastases." (PMID 29707138, 2018). "The RNF2 expression found in melanomas was significantly higher and it was even more enhanced in metastases." (PMID 29707138, 2018). "It was found that induction of enhanced RNF2 expression supported invasiveness of melanoma cells in vitro and metastasis of melanomas in immunodeficient mice." (PMID 29707138, 2018). "The expression of RNF2 in primary melanomas was significantly higher with 70% of the positively stained melanocytes and increased to 80% of RNF2 – positive cells in nodal metastases." (PMID 29707138, 2018). "Besides RNF6, another RNF protein, RNF2, is also reported to possess dual roles in the regulation of oncogenic gene networks via transcriptional upregulation of Cyclin D2 in melanoma." (PMID 34611311, 2021). "RNF2 also induces the expression of Cyclin D2 and thus drives proliferation of melanoma cells." (PMID 33670160, 2021). "For a sake of comparison between our results on the prognostic value of the RNF2 expression in melanoma and the data published earlier, we analyzed also the correlation between the I parameter values determined for the primary and metastatic lesions taken as one group and the patients’ survival." (PMID 29707138, 2018). "The lowest RNF2 expression was observed in nevi, significantly higher in primary melanomas (even at early stages like I and II Clark level; P = 0.006) and the highest in nodal melanoma metastases." (PMID 29707138, 2018). "The most significant result of the present study seems to be, however, finding that enhanced level of the intratumoral RNF2 expression may be a favorable prognostic indicator for the patients with both primary melanomas and nodal metastases." (PMID 29707138, 2018).
melanoma (continued). "The percentage fractions of the RNF2 – positive cells were determined for both primary and metastatic lesions and correlated with patients’ survival times and with the major clinico-pathological prognostic factors for melanoma." (PMID 29707138, 2018). "Therefore the aim of the present study was to assess the prognostic power of RNF2 intratumoral expression by melanoma cells." (PMID 29707138, 2018). "Using the scoring system accounting for the staining intensity of individual cells did not result in a better determination of a role of RNF2 levels as melanoma prognostic factor." (PMID 29707138, 2018). "However, RNF2 also mono-ubiquitinates H2A at lysine K199 at the promoter of the latent-transforming growth factor beta-binding protein 2 (LTBP2), resulting in the activation of TGF-β signaling and invasion of melanoma cells." (PMID 33670160, 2021). "Changes in the expression of RNF2 were independent of the prognostic factors like ulceration (P = 0.3), mitotic index (P = 0.6), histologic type (P = 0.8) and growth phase (P = 0.4) of the primary melanomas (Mann–Whitney U test)." (PMID 29707138, 2018). "In melanoma, RNF2 has been shown to be oncogenic and prometastatic, and RNF2 can promote metastasis through the inhibition of LTBP2, while its oncogenic function does not require it catalytic activity and RNF2 promotes cell proliferation through direct transcriptional upregulation of CCND2." (PMID 28029659, 2017).